CYP8B1 (cytochrome P450 family 8 subfamily B member 1)
Diseases named in the same sentence as CYP8B1 in open-access papers (continued):
Sharing a sentence is not in itself a finding about the gene and the disease.
steatosis (2 papers, 2007 to 2016). Increased lipid within the cytoplasm of cells. "In conclusion, following exposure to a high fat diet, Cyp8b1-/- mice are more resistant against weight gain, steatosis, and to glucose intolerance than Cyp8b1+/+ mice." (PMID 26824238, 2016). "In addition, liver enlargement with steatosis and increases in serum LDL-cholesterol were strongly attenuated in Cyp8b1-/- mice on high fat diet." (PMID 26824238, 2016). "Therefore, a reduction in lipid absorption is likely to in part explain why Cyp8b1-/- mice are more resistant to HFD-induced weight gain, steatosis, and to glucose intolerance." (PMID 26824238, 2016).
Ad- (1 paper, 2021). "Consistently, Ad-MAFG infection decreased the luciferase activities of the reporters containing Cyp7b1, Cyp8b1, and Cyp27a1 promoters in hepatocytes, respectively." (PMID 33754066, 2021).
fibrosis (1 paper, 2022). the formation of excess fibrous connective tissue in an organ or tissue in a reparative or reactive process. "The mRNA levels of Cyp8b1 and cytochrome P450, family 27, subfamily a, polypeptide 1 (Cyp27a1) were significantly decreased in the fibrosis groups." (PMID 35637968, 2022).
Glucose intolerance (1 paper, 2016). Glucose intolerance (GI) can be defined as dysglycemia that comprises both prediabetes and diabetes. "Several mouse models that are resistant to dietary induced glucose intolerance share phenotypic traits with Cyp8b1-/- mice e.g. an enlarged BA pool enriched in MCAs." (PMID 26824238, 2016). "We hypothesized that the presence of high levels of MCAs would be important for this resistance and that, accordingly, Cyp8b1-/- mice should be resistant to glucose intolerance as well." (PMID 26824238, 2016). "We hypothesized that high levels of MCAs may be important for the resistance against impaired glucose metabolism and that Cyp8b1-/- mice therefore should also be resistant to glucose intolerance." (PMID 26824238, 2016). "The current results showing that also Cyp8b1-/- mice are resistant to glucose intolerance, suggest that the very absence of a microbiota may not be key, lending support for the possibility that altered BA level and composition could be important since BAs regulate the microbiota." (PMID 26824238, 2016).
lipid metabolism disorders (1 paper, 2025). "The CYP8B1-cholic acid metabolic axis may represent a novel mechanism through which OJO improves glucose and lipid metabolism disorders, warranting further research to confirm this." (PMID 41357863, 2025).
pulmonary embolism (1 paper, 2018). The obstruction of the pulmonary artery or one of its branches by an embolus, sometimes associated with infarction of the lung. "Although a patient with rs202192572 on CYP8B1 did not have pulmonary embolism, this is also a rare East Asian-specific variant that was found in only five EAS subjects in T1GP." (PMID 29368655, 2018).
type 1 diabetes (1 paper, 2024). "The expression of hepatic CYP8B1 is regulated exactly as HSDL2: It is (i) increased upon fasting, (ii) activated by PPARα agonists, (iii) repressed by insulin, and (iv) elevated in type 1 diabetes." (PMID 38820148, 2024).
ulcerative colitis (1 paper, 2025). An inflammatory bowel disease involving the mucosal surface of the large intestine and rectum. "Previous work has revealed that the classical CYP8B1-CA metabolic pathway is significantly activated in both ulcerative colitis patients and experimental colitis mouse models." (PMID 41228488, 2025).
tumor (9 papers, 2015 to 2023). "When the anatomical site of the tumour was stratified as proximal colon, distal colon or rectum, significant associations were found with expression of CYP8B1, CYP27A1 and CYP51A1." (PMID 27341022, 2016). "The deletion of CYP8B1 and amplification of MGST3 were simultaneously associated with tumor grade, stage, and LNM in ESCC." (PMID 36168622, 2022). "Patients with strongly staining tumours for CYP8B1 (n=118) survived a mean of 79 months (95% CI 67-91) whereas negative/weak/moderate CYP8B1 immunostaining was associated with a better prognosis and a mean survival of 123 months (95% CI 114-132)." (PMID 27341022, 2016). "Strong immunostaining for CYP51A1 was demonstrated in 21.9% of tumours and CYP8B1 immunoreactivity was classified as strong in 18.9% of tumours." (PMID 27341022, 2016). "The mean survival for CYP8B1 moderately expressing tumours (n=133) was 101 months (95% CI 89-113) and the mean survival for CYP8B1 strongly expressing tumours (n=118) was 79 months (95% CI 67-91)." (PMID 27341022, 2016). "The mean survival in patients with tumours that did not express CYP8B1 (n=201) was 128 months (95% CI 113-141), declining to 119 months (95% CI 104-134) for tumours with weak CYP8B1 immunostaining (n=171)." (PMID 27341022, 2016). "Furthermore, we found that the bile acid biosynthesis genes Cyp8b1 and Baat were also increased in the tumor tissues of the low tumor group (GM:LEW) compared to Pirc rats in the GM:F344 group." (PMID 37458451, 2023). "Therefore, to further confirm that they indeed change at protein level consistent with the genome level, we performed IHC in tissue arrays to examine the protein levels of MGST3 and CYP8B1 in ESCC tumor tissues and adjacent normal tissues." (PMID 36168622, 2022). "Among these genes, CYP8B1 was suggested to be involved in tumor initiation and development." (PMID 34360670, 2021). "Promoter of some of the carcinogen-metabolizing genes like CYP8B1 and GSTA3 was found to be hypomethylated, specifically, in the tumor tissues of OSCC patients in India." (PMID 28174608, 2017). "CYP7B1, CYP8B1, CYP39A1, CYP46A1 and CYP51A1 each displayed a statistically significant relationship with location of tumour in the colon versus the rectum." (PMID 27341022, 2016). "When the primary tumours of lymph node positive cases (Dukes C, stage 3) were compared to the paired lymph node metastasis, expression of CYP2R1, CYP8B1, CYP39A1, CYP46A1 and CYP51A1 were each significantly reduced in the lymph node metastasis." (PMID 27341022, 2016). "The mean survival in patients with tumours showing negative/weak CYP8B1 immunoreactivity (n=371) was 126 months (95% CI 115-136) compared to 91 months (95% CI 82-99) in patients with tumours showing moderate/strong immunoreactivity (n=251)." (PMID 27341022, 2016). "Comparing CYP8B1 negative/weak/moderate tumours with CYP8B1 strongly expressing tumours demonstrated a highly significant relationship with survival (HR=1.649, 95% CI=1.268-22.145, χ2=14.298, p<0.001)." (PMID 27341022, 2016).
cancer (5 papers, 2014 to 2023). A tumor composed of atypical neoplastic, often pleomorphic cells that invade other tissues. "SHP is an orphan nuclear receptor that is regulated by many other nuclear receptors and transcription factors involved in metabolism and cancer and also has been shown to be involved in control of Cyp8b1 expression." (PMID 25506828, 2014). "CYP3A4 and CYP8B1 are the members of cytochrome P450 family which may rely on the function of metabolic carcinogens to play a vital role in chemoprevention, carcinogenesis, cancer therapy and metastasis." (PMID 34257549, 2021). "CYP450 plays crucial roles in these intertwined mechanisms of cholesterol homeostasis, such as CYP7A1, 27A1, 46A1, CYP8B1, and CYP39A1, which are cholesterol oxidation products whose expression may be dysregulated in inflammation-related diseases, including cancer." (PMID 35003516, 2021).
infection (4 papers, 2018 to 2025). The state of being infected such as from the introduction of a foreign agent such as serum, vaccine, antigenic substance or organism. "Oral administration of C. difficile VPI10463 spores resulted in no disease in C. scindens colonized animals, whereas germ-free Cyp8b1 mice rapidly succumbed to infection irrespectively of genotype." (PMID 34665847, 2021). "Infection of germ-free Cyp8b1-/- mice with spores derived from the C. difficile JSC10 strain resulted in identical clinical symptoms, and fulminant disease as the C. difficile UK1 strain." (PMID 34665847, 2021). "We thus determined whether infection with the S. Typhimurium wild type decreased expression of genes involved in bile acid synthesis, including Cyp7a1, Cyp8b1, Cyp27a1, and Cyp7b1." (PMID 40938708, 2025). "Similar to the prior work, Cyp8b1-/- mice still supported infection by C. difficile spores." (PMID 34665847, 2021). "In contrast, the mRNA and protein levels of hepatic CYP7B1, CYP8B1, and CYP27A1 were all increased by Ad-378 infection and decreased by Ant-378 administration, respectively." (PMID 33754066, 2021). "Similar results were obtained in primary murine hepatocytes after Ad-378 infection or Ant-378 transfection, suggesting that miR-378 regulates hepatic CYP7B1, CYP8B1, and CYP27A1 expression in a cell-autonomous manner." (PMID 33754066, 2021). "Since synthetic agomir for miR-378* (AgomiR-378*) transfection could not affect the mRNA expression of CYP7B1, CYP8B1, and CYP27A1, we speculated that miR-378 but not miR-378* contributes to the effect of Ad-378 infection on the expression of these enzymes." (PMID 33754066, 2021).
metabolic disease (4 papers, 2021 to 2025). A congenital disorder (due to inherited enzyme abnormality) or acquired (due to failure of a metabolically important organ) disorder resulting from an abnormal metabolic process. "The metabolic role of CYP8B1 has been recently explored; thus, CYP8B1 inhibition may offer a promising therapeutic avenue for treating metabolic diseases." (PMID 33447732, 2021).
liver (1 paper, 2015). "Furthermore, the upregulation of bile acid synthetic enzymes CYP7B1 and CYP8B1 may be attributed, at least in part, to FXR reduction, which is associated with increased expression of their suppressors HNF4α and LRH-1 in human obstructive cholestatic liver." (PMID 25798860, 2015).
CYP8B1 also shares sentences with these, for which no sentence is quoted: alcohol (1 paper); endothelial dysfunction (1); fungal infection (1); Hyperglycemia (1); hypertriglyceridemia (1); Hypocholesterolemia (1).